Y_RNA (Y RNA )
Gene: Miscellaneous RNA gene on chromosome 6 (106,454,828 to 106,454,929, forward strand). Ensembl gene ENSG00000200314.
Homologues: Orthologues: chimpanzee Y_RNA (98% identical), guinea pig Y_RNA (96% identical), macaque Y_RNA (94% identical). Paralogues in human: RNY3 (95% identical), Y_RNA (95% identical), Y_RNA (94% identical), RNY3P1 (93% identical), Y_RNA (93% identical), Y_RNA (92% identical), Y_RNA (91% identical), Y_RNA (90% identical), RNY3P14 (89% identical), Y_RNA (89% identical), RNY3P11 (88% identical), RNY3P16 (88% identical), and 98 more.